GLO1 (glyoxalase I)
Description:
Catalyzes the conversion of hemimercaptal, formed from methylglyoxal and glutathione, to S-lactoylglutathione. Involved in the regulation of TNF-induced transcriptional activity of NF-kappa-B. Required for normal osteoclastogenesis (By similarity).
Synonyms: GLOD1; GLYI; HEL-S-74
Tractability: Small molecule: a structure with a bound ligand is known; a high-quality ligand is known; it has a binding pocket of medium quality; it belongs to a druggable protein family. Antibody: its Gene Ontology location is reachable by antibodies, with high confidence; the Human Protein Atlas places it where antibodies can reach. PROTAC: ubiquitination databases record sites on it; its protein half-life has been measured; a small molecule that binds it is known.
Target class: Enzyme; Lyase
Gene: Protein-coding gene on chromosome 6 (38,675,925 to 38,703,145, reverse strand). Ensembl gene ENSG00000124767.
Subcellular location (Human Protein Atlas): Cytosol; Nucleoplasm; Plasma membrane
Pathways (Reactome):
Metabolism: Pyruvate metabolism
Gene Ontology:
Molecular function: lactoylglutathione lyase activity; protein binding; zinc ion binding; metal ion binding
Biological process: negative regulation of apoptotic process; carbohydrate metabolic process; osteoclast differentiation; glutathione metabolic process; methylglyoxal metabolic process
Cellular component: cytosol; extracellular exosome; nucleoplasm; plasma membrane; cytoplasm
Homologues: Orthologues: chimpanzee GLO1 (99% identical), macaque GLO1 (98% identical), rat Glo1 (91% identical), mouse Glo1 (90% identical), guinea pig GLO1 (89% identical), pig GLO1 (88% identical), dog GLO1 (86% identical), zebrafish glo1 (70% identical), Drosophila melanogaster Glo1 (65% identical). Paralogues in human: GLOD4 (27% identical).
Diseases named in the same sentence as GLO1 in open-access papers:
GLO1 is named in the same sentence as 177 diseases in open-access papers, as found by Europe PMC text mining. Sharing a sentence is not in itself a finding about the gene and the disease. The quoted sentences say what the papers report.
diabetes (82 papers, 2010 to 2025). "The reduced capacity of GLO-1 to detoxify MG has been observed in the case of the endothelial dysfunction that precedes the pathogenesis of diabetes-associated micro- and macrovascular complications." (PMID 38399319, 2024). "Induction of expression of Glo1 offers a new druggable target to counter activation of UPR in diabetes and other dicarbonyl stress-linked disorders." (PMID 38199038, 2024). "Research has shown that Glo1 expression and activity can vary among individuals and can influence susceptibility to certain diseases, including diabetes and its complications." (PMID 38723008, 2024). "Elevated levels of MG have been linked to diabetes, cardiovascular disease, and cancer, potentially due to the down-regulation of GLO1 expression and activity." (PMID 38027126, 2023). "The aim of this study was to develop an understanding of how Glo-1 interacts with other genes associated with inflammation, oxidative stress, and the micro- and macrovascular complications of Type 2 Diabetes Mellitus." (PMID 37759966, 2023). "Reduced capacity of Glo-1 to detoxify MGO has been observed in the case of endothelial dysfunction that precedes the pathogenesis of diabetes-associated micro- and macrovascular complications." (PMID 37759966, 2023). "Crocin prevents the progression of diabetes through modulating ER stress-associated microRNAs and GLO1 activity with the helpful effects of glutathione and Nrf2." (PMID 35655590, 2022). "In fact, decreased Glo1 phosphorylation has been associated with a decline in Glo1 activity in diabetes or ageing, whereas the opposite effect seems to take place in human tumor cells, in which Glo1 activity is usually upregulated." (PMID 33019494, 2020). "Hyperglycemic episodes and therefore diabetes related late complications, such as nephro-, retino- and neuropathy, have been frequently linked to increased MG levels due to a lower Glo1 expression in humans." (PMID 33019494, 2020). "An important finding of this recent study was the association of phosphorylated Glo1 with diabetes, ageing and malignant cells." (PMID 33019494, 2020). "Given the association between GLO1 and obesity and diabetes-related conditions, it represented an intriguing candidate for further investigation." (PMID 29456458, 2018). "Very recent evidence obtained in Glo1 over-expressing mice has shown that MGO increases inflammation in diabetes, leading to endothelial cell loss and, thus, contributing to the development of diabetic cardiomyopathy." (PMID 28106778, 2017). "A second approach to evaluating the possible impact of GLO-1 polymorphism on the onset of diabetes or diabetic complications is via the blocking of AGE accumulation on target organs." (PMID 28106734, 2017). "GLO1 gene polymorphism has been reported in some diseases other than breast cancer including, diabetes mellitus and its complications, epilepsy and autism spectrum disorder." (PMID 29321821, 2017). "MGO accumulation, perpetuated by Glo1 down-regulation, is linked to age-related diseases, such as diabetes, obesity, disorders of the central nervous system and cardiovascular disease, which share endothelial dysfunction as a common pathological denominator." (PMID 28106778, 2017). "In summary, new treatment strategies to reduce the dicarbonyl load and associated complications in diabetes include GLO1 inducer and improved scavenger molecules." (PMID 28475116, 2017). "This review focuses on the current understanding of MGO accumulation and Glo1 activity in diabetes, and their contribution on the impairment of endothelial function leading to diabetes-associated vascular damage." (PMID 28106778, 2017). "The aim of this commentary is to further highlight the potential importance of MGO and GLO1 in risk prediction, pathogenesis and intervention in vascular disease in people with diabetes." (PMID 25962521, 2015).
diabetes (continued). "In the GA-fed diabetic rats, the decrease in synaptophysin, TH, GS, and GLO1 caused by diabetes was attenuated by about 58%, 55%, 79%, and 53%, respectively." (PMID 24733965, 2014). "GLO1 is a detoxifying enzyme that has been implicated in a number of diseases, such as mood disorders, autism, anxiety, schizophrenia, diabetes, cancer, as well as aging and AD." (PMID 41100182, 2025). "Consequently, enhancing GLO-1 activity or expression in diabetic patients has been proposed as a therapeutic strategy to prevent and treat diabetes-associated complications." (PMID 40727469, 2025). "Additionally, diabetes altered the expression of genes associated with oxidative stress, DNA damage, heart fibrosis, and inflammation, which was partially attenuated by Glo1 overexpression." (PMID 38067472, 2023). "However, there have been limited studies evaluating the association between GLO1 and diabetes, especially gestational diabetes mellitus (GDM)." (PMID 38027126, 2023). "GLO1 gene SNP variants may impact its expression and activity and have been associated with diabetes risk." (PMID 38027126, 2023). "In addition, diabetes and its microvascular complications (nephropathy, retinopathy, and neuropathy), are associated with elevated levels of MG and reduced levels of GLO1 expression and activity." (PMID 33143048, 2020). "Additionally, microvascular complications of diabetes linked to high glucose concentration in retinal pericytes were prevented by overexpression of Glo1." (PMID 33143048, 2020). "MG/GLO1 has been causally linked to several late diabetic complications and may be upstream most of the pathological mechanisms observed in diabetes [7,]." (PMID 31254735, 2019). "Glo1 is reportedly associated with many diseases, including diabetes, cancer, and depression." (PMID 31822263, 2019). "Furthermore, Glo1 suppression has also been linked to the development of the vascular complications of diabetes and also to nephropathy, retinopathy, neuropathy, and cardiovascular disease." (PMID 31822263, 2019). "The question of whether GLO-1 polymorphism is related to the onset of diabetes or diabetic complications therefore warrants investigation." (PMID 28106734, 2017). "Diabetes is associated with tissue-specific down regulation of Glo1 and increased MG, which may increase risk of NET tumourigenesis." (PMID 29100361, 2017). "GLO1 expression may protect cells against methylglyoxal-dependent protein adduction and cellular damage associated with diabetes, cancer, and chronological aging." (PMID 27755556, 2016). "A gene functionally linked to obesity and diabetes is the glyoxalase 1 (Glo-1) gene, GLO-1." (PMID 27338619, 2016). "A reduced capacity of Glo1 to detoxify methylglyoxal is associated with endothelial dysfunction, nephropathy, and neuropathy, all of which represent important features of microvascular complications associated with diabetes mellitus." (PMID 26788517, 2016). "A recent study has confirmed that GLO1 protects against neuropathic pain associated with diabetes." (PMID 23181072, 2012). "Similarly, Glo1 copy number was associated with mechanical pain sensitivity after induction of diabetes in two closely related inbred strains, BALB/cJ and BALB/cByJ." (PMID 23181072, 2012). "After diabetes induction, A/J mice, which carry a triplication of the Glo1 allele, were less sensitive to mechanical pain than B6 mice, which have only a single copy of Glo1." (PMID 23181072, 2012). "We hypothesize that diabetes-induced impaired collateral formation after a hindlimb ligation in rats is in part caused by intracellular glycation and that overexpression of glyoxalase-I (GLO-I), i.e. the major detoxifying enzyme for advanced-glycation-endproduct (AGE) precursors, can prevent this." (PMID 27296676, 2016).
diabetes (continued). "We examined skin sections from Trpa1+/+ and Trpa1−/− mice treated with the GLO-1 inhibitor or vehicle for 2 weeks to assess whether the hypersensitivities produced by inhibition of GLO-1 were accompanied by a loss of IENFs, similar to that seen in mouse models of diabetes." (PMID 24167592, 2013). "From the animal, cellular, and molecular levels, the mechanism of PCA to improve oxidative stress in diabetic cataract by regulating GLO1 to inhibit AGE-RAGE glycosylation was verified." (PMID 40635755, 2025). "Several studies on manipulating Glo1 levels in cell and animal models have demonstrated its crucial role against diabetes." (PMID 39595078, 2024). "In Drosophila melanogaster, knockout of Glo1 accelerates diabetes progression, increases MGO concentrations, promotes lipid accumulation, elevates blood glucose levels, and decreases insulin sensitivity." (PMID 39595078, 2024). "Glo1 is especially important in cells and tissues exposed to high levels of oxidative stress, such as those with increased glucose metabolism, as seen in diabetes." (PMID 38723008, 2024). "GLO-1 overexpression in rats with streptozotocin (STZ)-induced diabetes reduces hyperglycemia-induced levels of carbonyl stress, AGEs, and oxidative stress." (PMID 37259448, 2023). "The MGO increase in murine models (MGO-fed or Glo1 inhibitor-treated apoE KO mice) to the level characteristic for diabetes has enhanced vascular adhesive properties, as well as atherogenesis." (PMID 38067472, 2023). "In instances of diabetes and metabolic disorders, there is an increase in MG that can surpass the intracellular detoxification capacity of GLO1, leading to the formation of advanced glycation end products (AGEs)." (PMID 38027126, 2023). "A protective effect of Glo1 overexpression against diabetes-induced cardiovascular impairment has been demonstrated in diabetic mice, in which it improved vascular inflammation and heart muscle condition." (PMID 38067472, 2023). "DN is a common complication that can occur with diabetes and involves the enzyme Glo-1 and alpha-carbonyl aldehydes." (PMID 38234970, 2023). "GLO1 inhibitors have been investigated for their effects on dicarbonyl stress in various pathologies, including atherosclerosis, diabetes and its vascular complications, osteoporosis, anxiety-linked behavior, and age-related decline in heart function." (PMID 37283758, 2023). "In STZ-treated rats, diabetes lowered Glo1 activity and upregulated some AGE markers (3-deoxyglucosone (3-DG) and CML) but had no impact on MGO and CEL levels in the rats’ hearts." (PMID 38067472, 2023). "Overexpression of Glo-1 is said to have a protective effect against reactive oxygen species (ROS), glucose-driven apoptosis, and dysfunction arising from angiogenesis and diabetes." (PMID 37759966, 2023). "The decreased activity/expression of GLO1 has been reported in diabetes neurodegenerative disorders, cardiovascular diseases and cerebrovascular diseases." (PMID 35455754, 2022). "Many researchers have reported the competing roles of MG, AGEs and GLO1 in the pathogenesis of diabetes and diabetic complications such as retinopathy, nephropathy and neuropathy." (PMID 35455754, 2022). "The complex and intricate roles of MG, AGEs and GLO1 in the pathogenesis of diabetes and diabetic complications such as retinopathy, nephropathy and neuropathy has also been reported." (PMID 35455754, 2022). "It has been shown that increased expression of Nrf2 and GLO1 improves diabetes-induced renal glucotoxicity through MGO detoxification." (PMID 36474578, 2022). "Recently, there have been many findings linking GLO1 to CNS degenerative diseases, hypertension, ageing, epigenetics, diabetes-related neurological complications, and several behavioural phenotypes." (PMID 36432007, 2022). "Conversely, normoglycemic mice with Glo1 knock-down display renal damage analogous to that seen in diabetics." (PMID 36135209, 2022).
diabetes (continued). "In diabetes models, Glo1 overexpression reduced glomerular protein modifications by MG, decreased oxidative stress markers, and prevented the development of diabetic kidney pathology." (PMID 34440621, 2021). "Given that the level of AGEs is dependent of blood glucose concentration, GLO1 expression and activity has also been investigated with regard to diabetes." (PMID 34440621, 2021). "Thiamine deficiency is common in MS; excess carbohydrate intake as HSS, and diabetes participate in enhancement of different glycation products following reduction of the activity of glyoxalase-I." (PMID 33995940, 2021). "Diabetes significantly decreased the expression of GLO1 and GSH in footpad skin compared with the control group." (PMID 34295304, 2021). "Previous studies have shown that GLO1 levels and activity can be altered in disease states, including diabetes, cardiomyopathy, and endothelial dysfunction." (PMID 34887734, 2021). "GLO1 levels and activity can be altered in disease states, including diabetes, cardiomyopathy, and endothelial dysfunction." (PMID 34887734, 2021). "Fisetin, a plant polyphenol found in many fruits and vegetables, promotes the expression and activity of GLO1, ameliorating major complications of diabetes in Akita mice, a model of type 1 diabetes." (PMID 34440621, 2021). "In rats, overexpression of Glo1 decreased diabetes-induced accumulation of MGO and MG-H1, oxidative stress and endothelial dysfunction, and attenuated early renal impairment." (PMID 33540757, 2021). "In agreement with mouse studies, rat models overexpressing human GLO1 led decreased MG levels, less AGEs formation, and reduced renal and endothelial dysfunction in response to induced diabetes compared with wild-type littermates." (PMID 33143048, 2020). "One reason for the development of late diabetic complications is the increase in MG-derived AGEs and DNA modifications, which is mainly due to the fact that Glo1 is downregulated in diabetes." (PMID 33019494, 2020). "GLO1 expression and activity are modified upon aging and in age-related diseases including diabetes and its microvascular complications such as DR." (PMID 33143048, 2020). "In diabetic mice, Glo1 overexpression also prevented diabetes-induced increases in MG modification of glomerular proteins, reduced oxidative stress, and prevented the development of diabetic kidney pathology, despite unchanged levels of hyperglycemia." (PMID 33143048, 2020). "In fact, many experimental and clinical studies confirmed that GLO1 inducers and/or dicarbonyl scavengers represent potential effective agents to reverse or limit diabetes-related complications." (PMID 31480513, 2019). "Glo1 reportedly plays an important role in many diseases, including diabetes, in which this gene is suppressed." (PMID 31822263, 2019). "It has been shown that overexpression of GLO1 in Glo1 transgenic mice prevented diabetes-induced MGO modification of glomerular proteins, increased oxidative stress, and the development of diabetic kidney disorders." (PMID 31388341, 2019). "It has been further demonstrated that NF-κB antagonizes the transcriptional activity of Nrf2, suggesting that in a pro-inflammatory state, typical of diabetes and obesity, NF-κB activation impairs Glo1 expression by inhibiting Nrf2 action." (PMID 28106778, 2017). "The presence of higher d-lactate levels alongside elevated GLO1 activity lends further support to the findings that GLO1 activity is elevated in diabetes." (PMID 28475116, 2017). "Decreased formation of MG-derived AGEs by GLO1 overexpression prevents ED in experimental diabetes with concomitant improvement of vascular function." (PMID 27898103, 2016). "Moreover, it is interesting that salicylate induced the gene expression of Glo1, which catalyzes the conversion of cytotoxic methylglyoxal to S-D-lactoylglutathione and D-lactate, which suppresses glycation-mediated cellular damage associated with diabetes and aging." (PMID 28042580, 2016).